TNF (tumor necrosis factor)
Diseases named in the same sentence as TNF in open-access papers (continued):
Sharing a sentence is not in itself a finding about the gene and the disease.
psoriasis (continued). "Other than having a role in MHC class I antigen presentation, ERAP1 is involved in the activation of inflammasome pathways and production of cytokines and chemokines involved in psoriasis development (i.e., IL-6, TNF-α, and CCL2)." (PMID 38495872, 2024). "The Food and Drug Administration (FDA) in the United States has approved TNF‐α inhibitors as a primary therapy for psoriasis." (PMID 39119034, 2024). "Network pharmacology revealed 259 active components targeting pathways in psoriasis, focusing on TNF, IL-6, and IL-1β." (PMID 38425649, 2024). "The first group of biologics available for the treatment of psoriasis was TNF-α inhibitors such as adalimumab, etanercept, infliximab, and certolizumab." (PMID 38832785, 2024). "An agent that is particularly correlated with cognitive impairment in depressive disorders and psoriasis is tumor necrosis factor (TNF)-alpha." (PMID 38892934, 2024). "TNF-α has been identified as a critical cytokine mediating cutaneous inflammation in the pathogenesis of psoriasis." (PMID 38793117, 2024). "A common cutaneous adverse reaction is the phenotypic switch from psoriasis to atopic eczema that occurs in up to 1%–12.1% of patients taking anti-TNF-α or anti-IL-17/IL-23 drugs." (PMID 38521706, 2024). "Obesity is associated with elevated levels of pro-inflammatory cytokines, such as TNF-α and IL-6, which play a role in the pathogenesis of both psoriasis and periodontitis." (PMID 39189252, 2024). "Given our patient’s clinical presentation, histological findings confirming psoriasiform dermatitis, and improvement after discontinuing anti-TNF treatment, we feel that her nasal mucosal lesions are most consistent with paradoxical psoriasis." (PMID 39403182, 2024). "TNF inhibitors are the first‐choice biologics based on the evidence for psoriasis and arthritis and are now available for use in Japan." (PMID 38105636, 2024). "While Th17 differentiation is induced by IL-6 and TGF-β, IL-23 is essential for Th17-cell function and production of key cytokines in psoriasis, such as IL-17A, IL-17F, IL-22, and TNF- α." (PMID 38731900, 2024). "The comprehensive medical history, clinical examination, and treatment response supported the diagnosis of TNF-α inhibitor-induced psoriasis." (PMID 39927272, 2024). "Psoriasis is a T cell–dependent disease that is usually successfully treated with therapies involving the inhibition of IL-12/IL-23/IL-17 and TNF-α axes." (PMID 39570671, 2024). "Tumor necrosis factor α inhibitors (TNFi) are a well-established treatment for moderate to severe psoriasis." (PMID 39409006, 2024). "A study comparing TNF-α inhibitors and brodalumab for psoriasis treatment found improvement in depressive symptoms with brodalumab but insufficient response with TNF-α inhibitors." (PMID 39408568, 2024). "TNF-α Inhibitors were the first biologics approved as a therapeutic option for both moderate and severe psoriasis and PsA." (PMID 38793117, 2024). "Levels of serum CRP and TNFα in NLRP3 genotypes of psoriasis patients were significantly different (P < 0.00001)." (PMID 38965465, 2024). "A significant proportion of psoriasis patients with Crohn’s disease and uveitis, but a smaller proportion with systemic lupus erythematosus and autoimmune thyroiditis were prescribed TNF-α inhibitors." (PMID 38957840, 2024). "These drugs inhibit TNF-α, thereby diminishing the downstream inflammatory cascade which plays a key role in the pathogenesis of psoriasis." (PMID 39409006, 2024). "HaCaT cells co‐stimulated with interleukin (IL)‐17, IL‐22, tumor necrosis factor‐alpha (TNF‐α), IL‐1α, and oncostatin M (M5) were used as an in vitro cell model of psoriasis." (PMID 39167035, 2024). "Psoriasiform reactions of anti-PD-1-treated patients were weakly immunoreactive for the type I IFN-α2A, at lower levels than paradoxical psoriasis induced by anti-TNF-α (~1.6-fold decrease)." (PMID 38495872, 2024).
psoriasis (continued). "In particular, this study highlights that IL-17 and TNF-α, two key cytokines in psoriasis pathogenesis, significantly alter AT secretory profiles and gene expression, promoting a pro-inflammatory state that impacts skin homeostasis." (PMID 39769200, 2024). "An estimated one case per 1,000 patient-years or 3-10% of patients receiving the treatment have anti-TNF-α-related psoriasis-like symptoms." (PMID 39463646, 2024). "TNF-a is also overexpressed in psoriasis, creating a link in etiologic mechanisms between psoriasis and CTCL, particularly a defect in the mechanisms involved in inducing cell death." (PMID 38607023, 2024). "In this study, all the inhibitors, mainly Iristatin, significantly decreased TNF-α expression during psoriasis development." (PMID 38444844, 2024). "This receptor is overexpressed in patients with psoriasis, and upon activation, mediates pathways that downregulate NF-κB signaling, reducing TNF expression and promoting an anti-inflammatory response." (PMID 38258121, 2024). "Recently, Rhodomyrtone (Rho), a compound extracted from Rhodomyrtus tomentosa, was reported to reduce skin inflammation in a psoriasis-like mouse model by inhibiting TNF-α expression." (PMID 38710713, 2024). "Concerning TNFα levels in response to psoriasis therapy, several studies found that serum levels of TNFα in patients with psoriasis were significantly higher than in the control group." (PMID 38965465, 2024). "Emerging evidence demonstrated a key role of IL-17, IL-23, and TNF-α and resulted in the development and approval of biological therapies that revolutionized psoriasis management." (PMID 38642273, 2024). "For psoriasis, these antibodies target tumor necrosis factor-α (TNF-α), as well as interleukins such as the interleukin (IL)-12/23 p40 subunit, IL-17A, IL-17 receptor (IL-17R), and the IL-23 p19 subunit." (PMID 39791046, 2024). "Advancements in our understanding of the pathogenesis of psoriasis have facilitated the identification of numerous potential therapeutic targets, including anti-tumor necrosis factor (TNF)-α, anti-interleukin (IL)-17, anti-IL-12/23, and anti-IL-23 therapies." (PMID 39857589, 2024). "For example, the NLR, PLR, neutrophil-to-monocyte ratio, and systemic immune-inflammation index were found to be useful biomarkers in tracking the response to treatment with TNF-α inhibitors in patients with psoriasis." (PMID 38673000, 2024). "Activated macrophages can produce cytokines such as TNF-α, IL-6, and IL-23, which are critical for the differentiation of Th17 cells, in psoriasis lesions." (PMID 38891893, 2024). "Therapies targeting NF-κB, such as TNF-α blockers and glucocorticoids, show promise in psoriasis treatment, but a delicate balance is required to avoid immunodeficiencies." (PMID 38892253, 2024). "One of the major unresolved mysteries is that psoriasis lesion often recur in the identical areas after the discontinuation of biologics targeting TNF-α, IL-23 and IL-17A/IL-17RA." (PMID 38347543, 2024). "The findings of this comprehensive review underscore the clinical significance of TNF-α inhibitors in managing atherosclerosis, particularly in patients with psoriasis and other rheumatic diseases." (PMID 39739136, 2024). "High levels of pro-inflammatory cytokines, such as IL-6 and TNF-α, are shared by psoriasis and depression, leading to alterations in serotonin, norepinephrine, and dopamine metabolism in the limbic system and basal ganglia, contributing to depressive symptoms." (PMID 39184643, 2024). "In psoriasis patients, both BMI and weight increased significantly with the use of anti-TNF-α therapies." (PMID 38185620, 2024). "We therefore analyzed psoriasis patients before starting established systemic therapy (targeting IL-17A, IL-23, TNF-α, IL-12/23, and DMF) and for a follow-up up to 16 weeks in a single-center prospective study." (PMID 38127137, 2024).
psoriasis (continued). "Patients with psoriasis have elevated levels of proinflammatory cytokines, such as IL-6 and tumor necrosis factor-alpha, contributing to systemic diseases." (PMID 39429270, 2024). "According to recent studies, elevated levels of tumor necrosis factor alpha; interleukins 1, 2, 10, 1 beta, 6 and 8; prostaglandin E2 and interferon gamma are suggested to be present in both psoriasis and depression." (PMID 38892934, 2024). "They exhibit anti-inflammatory properties by inhibiting key cytokines such as TNF-α, IL-6, IL-8, and IL-24, which play pivotal roles in the pathogenesis of psoriasis." (PMID 39199158, 2024). "All these monoclonal antibodies block the IL-17 signalling, improving psoriasis with remarkable efficacy and rapidity, more than TNF-α and IL-23 inhibitors." (PMID 39634792, 2024). "The inflammatory cytokines, TNF-alpha (Tumor Necrosis Factor-alpha) and IL-17A (Interleukin-17A), are related to psoriasis and have been pointed out to damage the autophagy function of keratinocytes." (PMID 38791423, 2024). "Elevated levels of tumor necrosis factor alpha (TNF-α), a well-known proinflammatory cytokine, have been identified in the skin and joints of individuals with psoriasis." (PMID 38672131, 2024). "Recent meta-analyses and observational studies have found no significantly increased risk of systemic malignancies, including lymphoma, with anti-TNF-α in psoriasis." (PMID 38610706, 2024). "When present with IL-22 or TNF-a, IL-17 induced the production of an antimicrobial protein that played a protective role when psoriasis lesions were combined with bacterial or fungal infections." (PMID 39480805, 2024). "Infliximab, for example, is a TNF inhibitor that is routinely used to treat patients with rheumatic diseases, psoriasis, and IBD." (PMID 38143258, 2024). "A variety of immune cells (T cells, DCs, and KCs) can release TNF-α, which plays multiple roles in the pathogenesis of psoriasis." (PMID 39296901, 2024). "Th17 is the predominant T-cell type driving psoriasis inflammation, secreting cytokines such as IL-17, IL-22, and TNF, that promote keratinocyte proliferation, angiogenesis, and epidermal hyperplasia." (PMID 38258121, 2024). "IMQ, a small-molecule immunomodulator, is known to induce psoriasis-like skin lesions in mice through mechanisms likely involving inflammatory cytokines such as TNF-α." (PMID 39465158, 2024). "This provides evidence that TNF-α inhibitors, represented by etanercept and adalimumab, can treat psoriasis by altering the composition of DCs." (PMID 38596682, 2024). "This process underscores the complex interplay within the IFNα-TNFα-IL-23-IL17 pathway core to psoriasis pathology." (PMID 38987260, 2024). "The treatment of keratinocytes with psoriasis-promoting cytokines IL17A/TNFα strongly changed the transcriptome." (PMID 39490928, 2024). "The treatment of psoriasis has undergone a revolution with the advent of biologic therapies, including tumour necrosis factor (TNF)-α, IL-23 and IL-17 inhibitors." (PMID 39634792, 2024). "IL-23 is the linking cytokine between innate and adaptive immunity and plays an essential role in maintaining inflammation, while IL-12 supports the production of cytokines essential in the pathogenesis of psoriasis, such as TNF and interferon-γ." (PMID 38473907, 2024). "Only 2-5% of patients receiving TNF inhibitors for other conditions, such as rheumatoid arthritis or inflammatory bowel disease, develop paradoxical psoriasis with generalized pustular psoriasis being among the least common presentations." (PMID 39781163, 2024). "Various cytokines, such as interleukin (IL)-17, IL-12, IL-23, and tumor necrosis factor-α (TNF-α), are considered hallmarks of psoriasis etiopathogenesis." (PMID 39063982, 2024).
psoriasis (continued). "The effects of the most frequent treatment options were also validated by testing the response of the system to the inhibition of IL-17, TNFα, IL-12, and IL-23, all of which are the main targets of the biologics used to treat moderate-to-severe psoriasis." (PMID 38303723, 2024). "Currently, targeted therapy with multiple cytokines has shown good efficacy in psoriasis, including TNF-α, IL-23, and IL-17 monoclonal antibodies." (PMID 39296901, 2024). "The results showed that HA-MTX-Lipo MNs inhibit the progression of psoriasis and reduce erythema, scaling, and thickening of the skin by down-regulating the expression of mRNA levels of pro-inflammatory cytokines IL-23 and TNF-α." (PMID 39598508, 2024). "Although inflammatory mediators like IL-22 and IL-17 have different functions in IBD and psoriasis as this is also evident in the targeted treatment response, IL-23 and TNF-α seem to play a crucial part in promoting inflammatory response in both disorders." (PMID 39463646, 2024). "The synergistic effects observed with the combination of IL-17 and TNF-α are particularly intriguing, as these cytokines are known to cooperate in amplifying immune responses in psoriasis." (PMID 39769200, 2024). "In a large-scale study that retrospectively analyzed various linear psoriasis presentations, the concept of anti-TNF-α inhibitor use unmasking linear psoriasis was discussed." (PMID 39665032, 2024). "The roles of cytokines such as TNFα, IL-15, IL-17, and IL-23 in psoriasis have been studied through mathematical/computational models as well as experiments." (PMID 38883205, 2024). "Th17 cells are critically involved in the pathogenesis of psoriasis by producing pro-inflammatory cytokines such as TNF-α, IL-17 and IL-22, which stimulate hyperproliferation and altered keratinocyte differentiation in psoriasis." (PMID 39331218, 2024). "A similar population of DCs, that express IL-23p19, TNF-a, and iNOS, is called slan (6-sulfo LacNAc) DCs (slanDCs) and contributes to psoriasis by producing IL-17 and IL-22." (PMID 38642273, 2024). "This dual nature of TNF-α in psoriasis and cancer highlights the complex role of immune dysregulation in both diseases." (PMID 39766123, 2024). "Several categories of biologic treatments have received regulatory approval for psoriasis, including TNF-α, IL-17, IL-12/23, and IL-23 inhibitors." (PMID 39311381, 2024). "The role of TNF-α is overriding in the pathophysiology of psoriasis, a chronic skin disorder characterized by aberrant immune system activation followed by accelerated cell turnover, resulting in the formation of thick, scaly, and red patches on the skin." (PMID 39063004, 2024). "Research has shown that sleep deprivation increases pro-inflammatory cytokines such as IL-6 and TNF-α in psoriasis." (PMID 39411067, 2024). "Randomized Clinical Trials (RCTs): Five RCTs have been conducted, all reporting that TNF-α inhibitors positively impact the progression of atherosclerosis in patients with psoriasis, PsA, and other rheumatoid diseases." (PMID 39739136, 2024). "Because of the clinical appearance, and positive data for sarcoidosis and approval for psoriasis in our case we opted for anti-TNF-α drugs." (PMID 39478628, 2024). "Tumor necrosis factor alpha antagonists (anti-TNFαs) have been widely used to treat autoimmune conditions including psoriasis, psoriatic arthritis, ankylosing spondyloarthropathies, rheumatoid arthritis, and inflammatory bowel disease." (PMID 39403182, 2024). "The originality of this study lies in the assessment of miR-155, miR-210, miR-205, and TNF-α in already-treated patients with psoriasis." (PMID 39044928, 2024). "Review of the literature indicates that biologics, such as TNF-α inhibitors, IL-12/IL-23 inhibitors, and anti-IL-17 inhibitors, generally have favorable effects on atherosclerosis in patients with psoriasis and PsA." (PMID 39739136, 2024).
psoriasis (continued). "The Multi-Analyte Flow Assay test showed that IMQ-induced psoriasis in mice had a notable effect on reducing IFN-γ, TNF-α, IL-9, IL-17F, IL-22, and IL-17A psoriasis-related inflammatory cytokines in the APLNs, Cal/Bms, and FA groups." (PMID 39534602, 2024). "In patients with psoriasis, TNF is overexpressed, amplifying psoriasis inflammation through multiple pathways." (PMID 38258121, 2024). "Given that both TNF-α and IL-6 are known to contribute to the onset and progression of NAFLD, the cause of this is most likely the elevated levels of both cytokines in psoriasis." (PMID 38707119, 2024). "TNFα is involved in the earlier events of psoriasis and drives the induction of dendritic cells and their maturation." (PMID 38303723, 2024). "Psoriasis (PsO) is a chronic skin condition driven by immune mediators like TNFα, INFγ, IL-17, and IL-23." (PMID 38405187, 2024). "Both breast cancer and psoriasis involve inflammatory cytokines such as TNF-α and IL-17/IL-23 axis, which play critical roles in immune system regulation." (PMID 39513840, 2024). "This was supported by the finding that the proportion of patients diagnosed with NMSCs within the first year after the start of anti-TNFα agents was found to be higher in psoriasis (36%) compared with RA (17%)." (PMID 38730981, 2024). "This study aims to investigate fungal gut microbiota changes in psoriasis patients transitioning from TNF-α inhibitors to brodalumab." (PMID 39408568, 2024). "In a study that analyzed the effects of punicalagin, the main chemical compound isolated from PG peel, on psoriasis, the authors used the imiquimod-induced psoriasis model in mice, as well as TNF-α- and IL17A-stimulated HaCaT cells." (PMID 38675119, 2024). "Biologics targeting IL-17A, IL-23, and TNF-α have been developed and approved for the treatment of psoriasis." (PMID 38893287, 2024). "In mild cases and controlled underlying disease, a “treat through” approach includes the continuation of the TNF inhibitor along with additional psoriasis treatments, such as topical corticosteroids, ultraviolet light therapy, and cyclosporine." (PMID 39781163, 2024). "Our assumption was made based on a study on the expression of miR-205 and other inflammation factors in chronic periodontitis, as we were not able to find studies referring strictly to the correlation between miR-205 and TNF-α in psoriasis." (PMID 39044928, 2024). "From studies it emerges that M1 macrophages contribute to the development of psoriasis, through production of TNFα." (PMID 38601151, 2024). "Adipose tissue acts as an endocrine organ, resulting in the formation of cytokines associated with both psoriasis and NAFLD (adipocytokines, adipokines (leptin and resistin) TNF-α, and IL-6)." (PMID 38473907, 2024). "Produced by various cell types associated with psoriasis, including keratinocytes, neutrophils, dendritic cells (DCs), mast cells, and Th22 cells, Th17, and NKT, TNF-α exhibits dual effects." (PMID 39311381, 2024). "In Japan, the first biologics for psoriasis were infliximab and adalimumab (anti–tumor necrosis factor α [TNF‐α] antibodies) introduced in 2010, followed by ustekinumab (anti–interleukin 12/IL‐23 subunit 40 [IL‐p40] antibody) in 2011." (PMID 38747075, 2024). "In 9.16% of cases, a therapeutic switch from IFX to ADA was required due to adverse effects, including allergic reactions, anaphylactic shock, psoriasis, or the development of anti-TNFα antibodies." (PMID 39677079, 2024). "There are two perspective cohort studies that have compared the effects of TNF-α inhibitors with IL-17 inhibitors, a relatively newer biologic treatment for psoriasis." (PMID 39739136, 2024). "Proinflammatory adipokines (TNF-α, IL-1, IL-6, and leptin) play a role in keratinocyte proliferation, and IL-1 is involved in molecular adhesion in the pathophysiology of psoriasis." (PMID 38473907, 2024).